APOE (apolipoprotein E)
Diseases named in the same sentence as APOE in open-access papers (continued):
Sharing a sentence is not in itself a finding about the gene and the disease.
cognitive decline (continued). "Unlike rodents, macaques possess highly developed association cortices with magnified calcium signaling, human-like inflammatory responses, and are naturally homozygous for ApoE-ε4-factors that together contribute to the spontaneous emergence of tau and amyloid pathology alongside cognitive decline." (PMID 41767744, 2026). "Whereas in sporadic PD the APOE ε4 allele was associated with faster cognitive decline than APOE ε3 or ε2 alleles, no APOE effect was observed in GBA1-PD or LRRK2-PD." (PMID 41730900, 2026). "Findings indicated that higher serum IgG antibodies to periodontal pathogens and elevated inflammatory mediators, notably tumor necrosis factor-alpha (TNF‐α), correlated with greater cognitive decline and markers of AD neurodegeneration, including MRI outcomes and APOE ε4 status." (PMID 41890452, 2026). "In AD, PGSs may explain additional disease risk beyond the apolipoprotein E (APOE) locus and have been associated with age of onset, disease progression, and clinical measures such as cognitive decline and biofluid and neuroimaging biomarkers." (PMID 41532810, 2026). "APOE ε4 carriers showed greater cognitive decline, especially in memory and visuospatial skills." (PMID 41085166, 2025). "Previous studies have found that adherence to a healthy lifestyle was associated with slower cognitive decline, regardless of the presence of the apolipoprotein E (APOE) ε4 allele." (PMID 39789005, 2025). "Another study based on a similar lifestyle definition in an American cohort also showed that more healthy lifestyle practices were associated with slower cognitive decline, irrespective of APOE ε4 allele presence." (PMID 40226865, 2025). "The distribution of APOE ε4 alleles did not correspond with the familial pattern of cognitive decline." (PMID 39912518, 2025). "For instance, Yaffe and colleagues found lower risk of cognitive decline with estrogen-only MHT use among female APOE ε4 non-carriers, but there was no such effect among carriers." (PMID 40439116, 2025). "However, the literature on how APOE ε4 influences the progression and manifestation of cognitive decline over the life span in healthy individuals remains mixed." (PMID 39903109, 2025). "Furthermore, the relationships between CSF ANGPT‐2 and longitudinal cognitive decline and APOE ε4 carriership are still undetermined and warrant further exploration." (PMID 40145342, 2025). "It is unclear why increased CSF ApoE levels might appear to protect against cognitive decline, but it is speculated that ApoE may be involved in injury repair mechanisms beyond Aβ amyloid plaques and tau NFT which linked to the cognitive changes." (PMID 40353050, 2025). "Moreover, in the presence of AD pathology, APOE-ε2 carriers present slower cognitive decline, while APOE-ε4 carriers experience faster decline compared with APOE-ε3 homozygotes." (PMID 40725224, 2025). "Second, the cross-sectional design precludes evaluation of whether speech kinematic differences in APOE-ε4 carriers evolve longitudinally or predict future cognitive decline." (PMID 41479611, 2025). "In patients with small subcortical infarctions, Aβ positivity has been identified as a significant predictor of PSCI development and cognitive decline over 1 year, suggesting that ApoE ε4 may influence PSCI through its role in Aβ accumulation." (PMID 40349252, 2025). "Each identified subgroup exhibited distinct patterns of cognitive decline across memory, executive function, and language domains, characterized by unique participant demographics, including baseline age, education level, and APOE ε4 carrier status." (PMID 40636900, 2025). "A phase III clinical trial of Tramiprosate in AD patients failed to meet the primary efficacy endpoints, but a subgroup analysis revealed significant cognitive improvements, measured by ADAS-Cog scores, and a positive trend on CDR-SB, in APOE-ε4 homozygous participants with milder cognitive decline." (PMID 41145344, 2025).
cognitive decline (continued). "This analysis examined whether the relationship between the APOE ε44 genotype and cognitive decline was mediated by brain volumes that were significantly reduced in APOE ε44 carriers compared to ε33/34 carriers." (PMID 39903109, 2025). "APOE ε4 carriers experience higher rates of cognitive decline in early and late onset AD." (PMID 41035086, 2025). "This shows that having the BDNF Met allele may prevent compensatory brain mechanisms in people with the APOE E4 gene, resulting in accelerated age-related brain changes and cognitive decline." (PMID 40360788, 2025). "Research centered on the role of APOE ε2 on cognitive decline is scarce, and the results are mixed." (PMID 41226628, 2025). "Studies have shown that individuals carrying the APOE e4 allele exhibit more significant memory impairment and cognitive decline compared to non-carriers." (PMID 39377784, 2025). "The efficacy of EGCG in combination with multimodal intervention (dietary guidance, physical exercise, psychoeducation, social activities and cognitive training) in slowing down cognitive decline was assessed in the PENSA study in APOE-ε4 carriers with SCD (NCT03978052)." (PMID 41145344, 2025). "The presence of ApoE ε4 and recurrent stroke did not appear to alter the association of education level with cognitive decline." (PMID 40136300, 2025). "We hypothesized that APOE homozygous ε4 carriers would exhibit more rapid cognitive decline and yield neuroanatomical changes with aging, while individuals with Klotho-VS heterozygosity would exhibit protective effects against such decline." (PMID 39903109, 2025). "In addition to the significant impact of the APOE genotype on mediating cognitive decline, studies have also emphasized the potentially crucial role of an individual’s sex." (PMID 39903109, 2025). "Overall, our analysis identified the APOE E4 haplotype as a reliable marker for cognitive decline." (PMID 41009775, 2025). "In addition, analyses stratified by APOE genotype, pre-stroke cognitive decline, and level of cSVD will be performed." (PMID 38570800, 2024). "Interestingly, a recent observational study found that only people with apoE ε4 isoform displayed an association between high BPV and cognitive decline." (PMID 39031528, 2024). "Additionally, the ability of the rate of change in the PiB-PET measures to predict cognitive decline was significantly influenced by APOE ε4 carrier status." (PMID 38150745, 2024). "Recent research work has indicated that APOE ε4 allele is not the only genetic factor implicated in objective cognitive decline among individuals with SCD." (PMID 38534745, 2024). "In this study, ApoE was associated with rapid cognitive decline in PD with p < 0.05, but it failed to pass multiple testing correction." (PMID 38988604, 2024). "The clinical data model consisting of demographics (age, sex, and education), baseline cognition (MMSE score, ADAS delayed word recall) and APOE status had a mean BioFINDER test R2 of 0.138 (CI -0.171–0.328) for predicting four-year cognitive decline as measured by MMSE." (PMID 38504336, 2024). "In stratified analysis by APOE genotype, the CR-cognitive decline association was similar in both ε4 carriers and non-carriers." (PMID 38706290, 2024). "Nonetheless, the authors themselves pointed out the need for further investigation into the relationship between cognitive decline and elevated SBP, as other factors such as the APOE allele may potentially modify this evidence." (PMID 38281243, 2024). "The absence of autopsy is a limitation since it could have reduced possible misinterpretations of the MR related CVSD lesions and future studies would benefit with information on ApoE status and family history of cognitive decline or PD." (PMID 39026021, 2024). "A longitudinal study (N = 912) found that APOE ε4 does not modify the association of neuroticism with cognitive ability and cognitive decline." (PMID 38984680, 2024).
cognitive decline (continued). "We then examined the differences between these three groups in terms of clinical diagnosis, APOE genotype, CSF phosphorylated tau (ptau) concentration, hippocampal volume, entorhinal thickness, and cognitive decline rate to evaluate the additional insights provided by the putamen beyond the cortex." (PMID 38397394, 2024). "For example, carrying the APOE e4 allele (APOE4), the strongest genetic risk factor for AD, may accelerate hippocampal atrophy, along with cognitive decline." (PMID 39135618, 2024). "Consistent with previous findings, we did not observe differences in ɛ4 frequencies between NC and SCD, supporting the hypothesis that SCD and APOE ɛ4 status independently influence longitudinal cognitive decline." (PMID 38253819, 2024). "Studies have shown that increased social interactions can provide cognitive challenges that stimulate neural circuits and reduce stress, fostering cognitive reserve and potentially buffering against the stress‐induced cognitive decline seen in APOE ε4 carriers." (PMID 39392181, 2024). "Increased atrophy of the temporal lobe has been linked to the presence of the APOE e4 allele and a higher risk of incident major depression irrespective of cognitive decline." (PMID 38473892, 2024). "More recently, studies have examined associations between PRS and cognitive trajectories in cognitively unimpaired and preclinical AD samples, with results showing that while PRS predicts cognitive decline, these effects are often primarily driven by APOE genotype." (PMID 38230720, 2024). "Collectively, these results suggest that the APOE e4 allele may be the primary genetic driver of the relationship between MBI psychosis and cognitive decline." (PMID 38473892, 2024). "The accelerated cognitive decline among apoE ε4 carriers may be due to the “tsunami effect,” in which large fluctuations of BP exacerbates apoE ε4‐associated vulnerability, such as a leaky BBB." (PMID 39031528, 2024). "Thus, the APOE genotype differences observed here in response to senktide injection suggest a critical need to more fully examine how symptoms associated with the menopausal transition, such as hot flashes, may contribute to cognitive decline and cognitive response to estrogen therapy." (PMID 39629477, 2024). "Indeed, cardiovascular risk factors have been associated with degradations in white matter microstructure, and carrying an APOE e4+ genotype exacerbates both cognitive decline and white matter deterioration." (PMID 38719452, 2024). "This study proposes an explanation for the observation that apoE protein levels, regardless of genotype, are associated with earlier cognitive decline in AD." (PMID 35484240, 2024). "It was shown that APOE in APOE ε4 carriers accelerates blood–brain barrier breakdown and degeneration of brain capillary pericytes through activation of the cyclophilin A-matrix metalloproteinase-9 pathway, leading to cognitive decline." (PMID 37109410, 2023). "Our work reveals that KL-VShet+ status enhances resilience to AD-related cognitive decline in male patients who do not carry the APOE ε4 allele." (PMID 37107675, 2023). "Some other studies found that ε2 was also a risk factor of cognitive decline in T2DM4, 7, 8; consistently, ApoE ε2‐carriers showed increased risk of cerebral amyloid angiopathy, a cerebrovascular disorder caused by deposition of amyloid Aβ aggregates and correlates with presenile cognitive decline." (PMID 37700547, 2023). "Our study demonstrates, for the first time, that KL-VShet+ status also slows down the progression of cognitive decline related to AD, and this effect is dependent on the absence of the APOE ε4 allele." (PMID 37107675, 2023). "In the present study, we aimed to determine whether the presence of the APOE-ε4 allele modifies the association between global and regional Aβ PET visual reads (VR) and cognitive decline in middle-aged CU individuals." (PMID 36856866, 2023).
cognitive decline (continued). "Second, to explore whether the surface‐based hippocampal morphometry measure could discriminate AD patients in different stages, future studies will add more samples of early stages of AD patients, such as ApoE 4 carriers and subjective cognitive decline." (PMID 37002795, 2023). "Finally, APOE ε4 carriers demonstrated faster cognitive decline following aging and hippocampus atrophy." (PMID 37323144, 2023). "Therefore, our results suggest that late Aβ deposition and APOE-ε4 carriership combine to determine cognitive decline in CU individuals." (PMID 36856866, 2023). "Analysis of longitudinal cognitive decline will further clarify whether APOE influences age of onset, rate of decline, or both." (PMID 37612284, 2023). "Additionally, studies also attempted to link genetic factors such as APOE genotypes with weight change and cognitive decline." (PMID 37628615, 2023). "APOE ε4 carriers induced more severe cognitive decline among individuals with hypertension." (PMID 38062190, 2023). "This likely reflects the fact that individuals at greater genetic risk (i.e., APOE-ε4 carriers; higher AD-PRS scores) have more AD pathology which at least partially underlies the relationship between these genetic risk factors and cognitive decline." (PMID 36978190, 2023). "We wonder whether the cognitive decline in ApoE ε4‐carried T2DM patients is mediated by the upregulation of GSK‐3β activity." (PMID 37700547, 2023). "The mechanisms by which hypertension and APOE ε4 gene collectively contribute to cognitive decline remain unclear." (PMID 38062190, 2023). "On top of this, literature supports the existence of additional mechanisms that may promote cognitive decline in CU APOE-ε4 carriers with higher Aβ accumulation." (PMID 36856866, 2023). "Next, we investigated whether the APOE-ε4 allele has an impact on the association between regional Aβ PET positivity and cognitive decline." (PMID 36856866, 2023). "For example, common genetic variation at GBA1 and APOE affects the rate of cognitive decline." (PMID 37842125, 2023). "We did not characterize ApoE genotype, a known risk factor for cognitive decline and amyloidosis in older individuals, but our previous work demonstrated that ApoE4 genotype did not increase the risk of HAND." (PMID 35674935, 2022). "When examining the association of OCRS with cognitive decline in the general population depending on APOE-ε4, it is not possible to derive an empirical test of a link to BR due to the lack of a direct measure of neurobiological resources." (PMID 36571008, 2022). "We found that higher OCRS is not generally related to slower cognitive decline in individuals aged 75 years or above from the AgeCoDe cohort; instead, it is associated with a reduction in the association of carrying an APOE-ε4 allele with cognitive decline." (PMID 36571008, 2022). "Besides, both Aβ pathology and vascular diseases are related to neurodegeneration and cognitive decline, but it is still not fully understood how APOE-ε4 modulates these relationships." (PMID 35351867, 2022). "Resilience towards cognitive decline generally observed among ɛ2 carriers could arise from relatively higher baseline APOE steady-state levels in regions including the HC and frontal cortex as compared to ɛ4 carriers and ɛ3 homozygotes." (PMID 36512526, 2022). "Two studies found the strongest cognitive decline in highly education APOE-ε4 carrier, while other studies showed no significant statistical interaction or a decreasing association of APOE-ε4 with cognitive decline as education increases." (PMID 36571008, 2022). "Notably, it was previously shown in AgeCoDe that specific cognitive demands are especially important in mitigating the relationship between APOE-ε4 and cognitive decline." (PMID 36571008, 2022).
cognitive decline (continued). "Recent evidence demonstrates that oligomeric Aβ, in the company of C3, C1q, and apolipoprotein E (APOE), can drive pathological pruning that may play a role in how Aβ oligomers cause loss of synapses and lead to cognitive decline." (PMID 36002854, 2022). "We suspected that the effects of CSF GAP-43 in the pathophysiology of cognitive decline may be relevant to APOE ε4 status." (PMID 36611808, 2022). "The current findings of significant differences and correlations could partly explain the effect of APOE ε4 on cognitive decline in hypertensive patients." (PMID 35624902, 2022). "The matrisome module was influenced by the APOE ε4 allele but was not related to the rate of cognitive decline after adjustment for neuropathology." (PMID 35115731, 2022). "We found that rs429358-C, one of the APOE SNPs, was associated with long-term general cognitive decline, but not with general cognitive function at baseline." (PMID 36446774, 2022). "Different phenotypes influenced by sex and genetics could also relate to cognitive decline: males with APOE ε4 had a steeper rate of cognitive decline." (PMID 35884724, 2022). "Furthermore, APOE ε4 carrier status is another key factor of cognitive decline in AD patients with VRFs." (PMID 36389060, 2022). "The non-AD studies reviewed in this article suggested a consistent finding of L and VL variants associated with a higher rate of cognitive decline independent of APOE isoform." (PMID 35964003, 2022). "In conclusion, we confirm that rs429358, and thereby the APOE locus, is significantly associated to general cognitive decline, but not to general cognitive function at baseline." (PMID 36446774, 2022). "However, even in the presence of ApoE ε4 and cognitive decline together are insufficient criteria for diagnosing Alzheimer’s." (PMID 35517054, 2022). "We did not observe a significant association between APOE ɛ4 and pRBD suggesting both factors having an independent effect on cognitive decline in iPD." (PMID 36245388, 2022). "Apolipoprotein E (APOE) genotype is the strongest genetic risk factor for late-onset AD and the ε4 allele has been recently associated with BBB dysfunction leading to cognitive decline." (PMID 35139885, 2022). "One recent study found APOE-ε4 only affected the associations of Aβ pathology with neurodegeneration and cognition, whereas did not modulate the associations of WMH with longitudinal neurodegeneration and cognitive decline." (PMID 35351867, 2022). "Considering this, the pattern of our results on OCRS and APOE-ε4 statistical interaction effects on cognitive decline is most consistent with OCRS mainly acting through CR or BR since the OCRS mitigates the association between APOE-ε4 and cognitive decline." (PMID 36571008, 2022). "This relationship between mindfulness and longitudinal cognitive decline remained significant when covariates (age, sex, education, APOE status, and time between completion of the FFMQ and baseline RBANS) were included in the model (β = 0.21, t = 3.55, p < .001)." (PMID 36712573, 2022). "More recently, researchers have also focused on understanding the relevance of APOE ε4 prevalence and the early stages of cognitive impairment, such as subjective cognitive decline (SCD), which is an intermediate stage between mild cognitive impairment (MCI) and normal cognition." (PMID 35720695, 2022). "First, APOE ε4 leads to a more severe phenotype of cognitive decline." (PMID 35149974, 2022). "Changing from a negative to positive amyloid status was associated with APOE ε4 carriership and predicted subtle cognitive decline, suggesting the potential clinical relevance of amyloid burden in the negative range." (PMID 36057616, 2022). "PART is a common neuropathological finding in the brains of over 85‐year‐olds, and individuals with PART differ from individuals with typical AD‐type neuropathological changes with regard to their pattern of cognitive decline, APOE genotype and burden of comorbid pathologies." (PMID 34927275, 2022).